OGN (osteoglycin)
Diseases named in the same sentence as OGN in open-access papers (continued):
Sharing a sentence is not in itself a finding about the gene and the disease.
cervical cancer (4 papers, 2020 to 2024). A primary or metastatic malignant neoplasm involving the cervix. "The results showed that the promotion on the proliferation, migration and invasion of cervical cancer cells caused by miR-5003-3p mimics could be reversed by OGN overexpression." (PMID 35513835, 2022). "EIF4A3-regulated circ_0087429 can reverse EMT and inhibit cervical cancer progression via miR-5003-3p-dependent up-regulation of OGN expression." (PMID 38814453, 2024). "circ_0087429 can be used as a molecular sponge of miR-5003-3p to reverse EMT by regulating the expression of the target gene OGN, thereby inhibiting the occurrence and development of cervical cancer." (PMID 35513835, 2022). "These target genes were crossed with mRNAs that are downregulated by more than fivefold in cervical cancer from The Cancer Genome Atlas (TCGA) database, and 8 target genes were finally obtained (OGN, SCN7A, PGR, PTGER3, FGF7, ADAMTS5, LMO3 and ANK2)." (PMID 35513835, 2022). "Correlation analysis showed that the expression levels of OGN and circ_0087429 in cervical cancer tissue were positively correlated." (PMID 35513835, 2022). "We assessed the expression of OGN in cervical cancer cells and tissues, and the results confirmed that OGN was significantly downregulated in cervical cancer." (PMID 35513835, 2022). "Later, it was verified that OGN expression is downregulated in cervical cancer and is closely related to tumour size in cervical cancer patients." (PMID 35513835, 2022). "As a tumour suppressor, circ_0087429 regulated by EIF4A3 can reverse EMT and inhibit the progression of cervical cancer through the miR-5003-3p/OGN axis." (PMID 35513835, 2022). "In summary, our research shows that there is a new tumour suppressor gene, circ_0087429, in cervical cancer; circ_0087429 can regulate the expression of its target gene OGN by competitively binding with miR-5003-3p, thereby inhibiting EMT in the occurrence and development of cancer." (PMID 35513835, 2022). "OGN is significantly downregulated in cervical cancer tissues and cells." (PMID 35513835, 2022). "Functional experiments showed that OGN has a tumour-suppressive effect, the tumour-promoting effect of miR-5003-3p in cervical cancer can be inhibited by the target gene OGN, and downregulation of OGN can also block the tumour-suppressive effect of circ_0087429." (PMID 35513835, 2022). "Among them, the target gene OGN was the most significantly downregulated in cervical cancer." (PMID 35513835, 2022). "The results showed that si-OGN could significantly reverse the inhibitory effect of circ_0087429 on the proliferation, migration and invasion of cervical cancer cells, indicating that the tumour suppressor effect of circ_0087429 was achieved through the miR-5003-3p/OGN axis." (PMID 35513835, 2022). "The role of miR-5003-3p and OGN in cervical cancer is still unknown." (PMID 35513835, 2022). "The specific role and regulatory mechanism of OGN in cervical cancer are still unknown." (PMID 35513835, 2022). "circ_0087429 can upregulate the expression of OGN by competitively binding with miR-5003-3p, thereby reversing EMT and inhibiting the progression of cervical cancer." (PMID 35513835, 2022). "In summary, EIF4A3-downregulated circ_0087429 is a tumour suppressor gene that can promote the expression of OGN and inhibit the EMT of cervical cancer cells by competitively binding miR-5003-3p." (PMID 35513835, 2022). "Given that both miR-5003-3p and OGN participate in EMT of tumours, we explored the influence of circ_0087429 on the EMT in cervical cancer." (PMID 35513835, 2022).
colon cancer (4 papers, 2018 to 2022). "The colon cancer cell lines were transduced with lentiviral constructs encoding human OGN cDNA to generate stable OGN over-expression cell lines (HCT116-OGN+, RKO-OGN+, SW620-OGN+, HT29-OGN+)." (PMID 29499765, 2018). "As results, in vitro and in vivo, the OGN expression was demonstrated to reduce cell proliferation, inhibit invasion of colon cancer cells then impede cancer progression." (PMID 29499765, 2018). "In colon cancer tissues, the three types of OGN+ fibroblasts were highly decreased or diminished." (PMID 36463319, 2022). "OGN could reverse epithelial-to-mesenchymal transition (EMT) and inhibit invasiveness in colon cancer cells." (PMID 33015704, 2020). "Since DCN was identified dominantly to be expressing in OGN+ fibroblasts, consistently, DCN staining was also dramatically decreased and did not encircle any cancer cells in colon cancer tissues." (PMID 36463319, 2022).
Myocardial fibrosis (4 papers, 2019 to 2024). "Silencing of osteoglycin has been suggested to exert inhibitory effects on myocardial fibrosis and EMT in a mouse model of myocarditis via downregulating levels of TGF-β1, FSP-1, α-SMA and upregulating levels of E-cadherin." (PMID 35264108, 2022). "Studies on osteoglycin knockout mice further suggest a beneficial function for osteoglycin in preventing aging-related myocardial fibrosis and diastolic dysfunction." (PMID 31547598, 2019). "Therefore, it is reasonable to deduce the expression of OGN active in cardiac fibroblasts in the context of HF, leading to myocardial fibrosis and remodeling post-HF." (PMID 38397416, 2024). "In a mouse model of myocarditis, OGN gene silencing inhibited proliferation of mouse myocardial fibroblasts and suppressed EMT and EndMT by activation of the Wnt signaling pathway, thus further resulting in the alleviation of myocardial fibrosis after myocarditis." (PMID 36421687, 2022).
atherosclerosis (3 papers, 2018 to 2023). A disease characterized by the build-up of fatty material and calcium deposition in the arterial wall resulting in partial or complete occlusion of the arterial lumen. "This analysis allowed us to evaluate the association between osteoglycin and atherosclerosis in a clinical context." (PMID 37819194, 2023). "Second, we conducted experiments using osteoglycin in VSMCs exposed to calcified environments in vitro, to examine the direct impact of this protein on the development of atherosclerosis." (PMID 37819194, 2023). "Overall, while acknowledging the limitations, our study contributes significantly to the understanding the role of osteoglycin in the context of atherosclerosis and T2D." (PMID 37819194, 2023). "This study aims to investigate the involvement of osteoglycin in the development of atherosclerosis in humans, which is highly controversial." (PMID 37819194, 2023). "By combining clinical and experimental investigations, our study aims to provide comprehensive insights into the role of osteoglycin in the processes of atherosclerosis in humans with T2D." (PMID 37819194, 2023). "NEW & NOTEWORTHY This study uncovers an increase of serum osteoglycin levels in patients with type 2 diabetes, which does not appear to be associated with the development of atherosclerosis, but rather with insulin resistance in this population." (PMID 37819194, 2023). "Osteoglycin could be a biomarker of insulin resistance for type 2 diabetes and could be indirectly involved in the development of atherosclerosis." (PMID 37819194, 2023). "Furthermore, osteoglycin could indirectly participate in the development of atherosclerosis through its regulatory effect on ATX and by proliferating VSMCs." (PMID 37819194, 2023). "Based on this, osteoglycin does not appear to be a key determinant in the pathogenesis of atherosclerosis in patients with T2D directly, although it may play an indirect role through its involvement in insulin resistance." (PMID 37819194, 2023).
fibrosis (3 papers, 2021 to 2024). the formation of excess fibrous connective tissue in an organ or tissue in a reparative or reactive process. "The CILP2 protein, also known as osteoglycin, attenuates cardiac fibrosis by suppressing cardiac myofibroblast proliferation." (PMID 39768140, 2024).
interstitial lung disease (3 papers, 2022 to 2024). A diverse group of lung diseases that affect the lung parenchyma. "In addition, overexpression of OGN contributes to the progression of interstitial lung disease (ILD) via the Wnt signaling pathway." (PMID 36421687, 2022).
myocarditis (3 papers, 2017 to 2022). Myocarditis is a condition that is characterized by inflammation of the heart muscle (myocardium). "In silico structure modeling predicted a potential interaction between the concave leucine-rich surface of OGN and the extracellular LRR domain of TLR4 that has been implicated in CVB3-myocarditis disease severity." (PMID 27878326, 2017). "Therefore, we subjected male OGN WT and KO mice to the murine model of CVB3-induced myocarditis." (PMID 27878326, 2017). "In conclusion, the absence of OGN decreases immune cell infiltration in CVB3-infected murine hearts, suggesting that increased expression of leukocyte-specific 72 kDa OGN in myocarditis aggravates cardiac inflammation in the acute phase of myocarditis." (PMID 27878326, 2017).
Obesity (3 papers, 2020 to 2023). Accumulation of substantial excess body fat. "Osteoglycin is a hormone highly expressed in adipose tissue and secreted into the circulation, in both mice and humans with obesity." (PMID 37819194, 2023). "Thus, the OGN pathway is an attractive target for potential novel treatment of obesity and type 2 diabetes." (PMID 37676424, 2023).
pulmonary fibrosis (3 papers, 2023 to 2025). Chronic progressive interstitial lung disorder characterized by the replacement of the lung tissue by connective tissue, leading to progressive dyspnea, respiratory failure, or right heart failure. "Interestingly, Huang and colleagues reported upregulation of OGN in lungs and myofibroblasts obtained from lung fibrosis murine models." (PMID 40133363, 2025).
type 2 diabetes (3 papers, 2023 to 2024). "On the other hand, osteoglycin decreased following weight loss which does not support that high BMI should cause higher osteoglycin levels in type 2 diabetes." (PMID 38549032, 2024).
cardiomyopathy (2 papers, 2017 to 2023). A disease of the heart muscle or myocardium proper. "Analysis of pathways that were dysregulated across cardiomyopathy phenotypes identified shared genes that were associated with extracellular matrix remodeling and thus likely fibrosis (THY1, CILP, OGN, THBS4, ASPN, HAPLN1,and SMOC2), as well as calcium (ADIPOQ, ASPN, THBS4, STAT4, and SMOC2)." (PMID 28098235, 2017).
chronic kidney disease (2 papers, 2018 to 2021). Impairment of the renal function secondary to chronic kidney damage persisting for three or more months. "OGN is involved in several biological processes and is related to various pathologies, such as bone fragility, cardiovascular disease (CVD), neurologic disease, ocular diseases, and chronic kidney disease (CKD), among others." (PMID 34065223, 2021).
diabetic nephropathy (2 papers, 2021 to 2022). "Linear regression modeling was performed to determine the variables influencing circulating OGN, and an ROC curve was plotted to assess the usefulness of OGN as an estimator of diabetic kidney disease risk." (PMID 34065223, 2021). "Decreased OGN as well as activation of the NF-κB signaling pathway were correlated with the pathogenesis of diabetic nephropathy." (PMID 36421687, 2022).
dyslipidemia (2 papers, 2018 to 2021). "Furthermore, OGN has been identified as a quantitative trait loci (QLT), relevant to the metabolic syndrome on chromosome 17." (PMID 29499765, 2018).
Insulin resistance (2 papers, 2019 to 2023). Increased resistance towards insulin, that is, diminished effectiveness of insulin in reducing blood glucose levels. "In conclusion, osteoglycin could play a role in glycemic homeostasis, being a potential biomarker of insulin resistance in patients with T2D." (PMID 37819194, 2023). "We demonstrated that osteoglycin plays a key role in glycemic homeostasis and could be a potential biomarker of insulin resistance in patients with T2D." (PMID 37819194, 2023). "We propose that the osteoglycin-mediated insulin resistance may be related to the ATX pathway." (PMID 37819194, 2023). "However, there is a potential relationship of osteoglycin with markers of insulin resistance." (PMID 37819194, 2023).
melanoma (2 papers, 2018 to 2025). A malignant, usually aggressive tumor composed of atypical, neoplastic melanocytes. "Many of these downregulated proteomic cargoes in melanoma sEVs, including collagens (COL1A1, COL3A1, COL6A1–A3, and COL14A1), matrix-associated proteoglycans (DCN, LUM, FMOD, OGN, and PRELP), and structural regulators (TNXB and PCOLCE), are key components of ECM organization and tensile strength." (PMID 41271007, 2025). "Hence, it was observed that ER stress-triggered cell death was attenuated by specific knockdown of OGN mRNA in melanoma cells." (PMID 29499765, 2018).
osteoarthritis (2 papers, 2014 to 2018). A noninflammatory degenerative joint disease occurring chiefly in older persons, characterized by degeneration of the articular cartilage, hypertrophy of bone at the margins and changes in the synovial membrane. "We also confirmed the expression of ANPEP, dickkopf WNT signaling pathway inhibitor 3 (DKK3) and osteoglycin (OGN) by multiple reaction monitoring (MRM) analysis of osteoarthritis synovial fluid samples." (PMID 24533825, 2014). "OGN has been reported to be elevated in osteoarthritis synovial fluid samples and may induce the mineralization and calcification of cartilage." (PMID 30355362, 2018).
thyroid tumor (2 papers, 2018 to 2023). A benign or malignant neoplasm affecting the thyroid gland. "Even more, OGN expression in normal tissue, benign follicular adenoma progressing to aggressive follicular cancer experienced a progressive decrease, indicating that the level of OGN expression paralleled thyroid tumor progression." (PMID 29499765, 2018).
viral myocarditis (2 papers, 2017 to 2019). Myocarditis that is caused by an infection with a viral agent. "This study uncovered a previously unidentified 72-kDa variant of OGN that is predominant in cardiac human and mouse samples of viral myocarditis." (PMID 27878326, 2017). "The sole presence of a new yet undescribed cardiac OGN variant of approximately 72-kDa was found in the murine hearts with viral myocarditis." (PMID 27878326, 2017). "SLRP’s may affect inflammatory and fibrotic processes, but the implication of OGN in cardiac inflammation and the resulting injury upon viral myocarditis is unknown." (PMID 27878326, 2017). "Aside from influencing cardiac inflammation in viral myocarditis, the interaction of OGN with TLR4 may also influence the development and progression of other cardiac diseases." (PMID 27878326, 2017). "The absence of OGN decreases cytokine production by both circulating and cardiac leukocytes upon (systemic) LPS exposure, and reduces cardiac inflammation and injury in viral myocarditis." (PMID 27878326, 2017).
aortic valve calcification (1 paper, 2022). "Among DEGs not related to humoral immunity many overlap with those already implicated in aortic valve calcification, these include TNC, PRG4, COL11A1, SMOC2, FN1, and OGN." (PMID 36437309, 2022).
colorectal tumors (1 paper, 2018). "OGN is expressed within the epithelial cancer cell and stromal compartments of human colorectal tumors." (PMID 29499765, 2018).
Duchenne muscular dystrophy (1 paper, 2023). Duchenne muscular dystrophy (DMD) is a neuromuscular disease characterized by rapidly progressive muscle weakness and wasting due to degeneration of skeletal, smooth and cardiac muscle. "Increased OGN levels have been shown in progressive myelofibrosis which plays a key role in Duchenne muscular dystrophy." (PMID 38322285, 2023).
endometrial cancer (1 paper, 2020). Primary or metastatic malignant neoplasm involving the endometrium (mucous membrane that lines the endometrial cavity). "On the other hand, HAND2-AS1, PEG3, OGN, SFRP4, WT1, FOXL2 and EFEMP1 were significantly lower in endometrial cancer tissues than in normal tissues." (PMID 32555395, 2020).
endotoxemia (1 paper, 2017). "We, therefore, subjected OGN WT and KO mice to endotoxemia, a model of septic shock where TLR4 activation is, in part, driving pathogenesis." (PMID 27878326, 2017). "To validate the interaction of OGN with TLR4 in vivo, we reasoned that a lack of OGN on circulating leukocytes in OGN null mice, may alter TLR4 signaling in the mouse model of endotoxemia." (PMID 27878326, 2017).
esophageal cancer (1 paper, 2020). A primary or metastatic malignant neoplasm involving the esophagus. "Esophageal cancer-related gene-4 inhibits the NF-κB signaling pathway by promoting NFIC/OGN signaling in BCa cells." (PMID 32922434, 2020).
head and neck squamous cell carcinoma (1 paper, 2022). A squamous cell carcinoma that arises from any of the following anatomic sites: lip and oral cavity, nasal cavity, paranasal sinuses, pharynx, larynx, and salivary glands. "OGN is also important in modulating the microenvironment and tumor biology in head and neck squamous cell carcinoma, according to a protein-protein interaction analysis (HNSCC)." (PMID 36421687, 2022).
hypertensive heart disease (1 paper, 2024). Abnormal enlargement of the heart resulting from long-standing hypertension. "Moreover, OGN was reported to modulate fibrosis and inflammation, resulting in diastolic dysfunction shown in hypertensive heart disease." (PMID 38397416, 2024).
kidney damage (1 paper, 2021). "Although future longitudinal studies are needed, our preliminary results place OGN as a promising biomarker that deserves future research to confirm its potential role as an early predictor of kidney damage in daily clinical practice." (PMID 34065223, 2021).
lung adenocarcinoma (1 paper, 2020). A carcinoma that arises from the lung and is characterized by the presence of malignant glandular epithelial cells. "Six genes (COL3A1, COL1A2, OGN, COL15A1, ASPN, and MXRA5) and three miRNAs (hsa-miR-29c-3p, hsa-let-7c-5p, and hsa-miR-29b-3p) were related to the survival time of lung adenocarcinoma (LUAD)." (PMID 32300359, 2020).
lupus (1 paper, 2025). "Four proteins, SNRPB/SNRPN, OGN, IFI27, FBLN2, identified only in extracellular vesicles in the blood of CLE patients were also proteins reported to be related to lupus and inflammation." (PMID 41614843, 2025).
lymph node metastasis (1 paper, 2021). "The transcription levels of CTGF, CYR61, FGF13, CHRDL1, and OGN were significantly higher in health controls than in THCA patients in the subgroup analyses involving disease stage, lymph node metastasis, gender, and age." (PMID 33816258, 2021).
malignant meningioma (1 paper, 2021). "Chrysophanol may be useful as a treatment against malignant meningioma by inhibiting OGN/mTOR signaling and activating NF2 signaling." (PMID 33622177, 2021). "In addition, osteoglycin (OGN) may help mediate the antitumor effects of chrysophanol; thus, this study investigated the potential antitumor mechanism of chrysophanol in malignant meningioma cultures." (PMID 33622177, 2021).
Pc (1 paper, 2024). "Closer examination suggested that OGN+/UCHL1+ cell abnormalities in proliferation and migration lead to abnormal Pc formation in hairless pigs and that BMP and TGFβ are the first signaling pathways that trigger OGN+/UCHL1+ cells to undergo Pc formation." (PMID 38561967, 2024).
prostate tumor (1 paper, 2023). "CRISP3 was upregulated; conversely, OGN, SPOCK3, COL4A6, CCBE1, and FLRT3 were downregulated in prostate tumor tissues." (PMID 37251946, 2023).
Retinal dystrophy (1 paper, 2016). Retinal dystrophy is an abnormality of the retina associated with a hereditary process. "For example, previous studies have associated OGN with bone and muscle formation and CYP4V2 is associated in man with retinal dystrophy." (PMID 27507242, 2016).